RNU6-44P (RNA, U6 small nuclear 44, pseudogene)
Synonyms: RNU6-44
Gene: Small nuclear RNA gene on chromosome 11 (112,352,556 to 112,352,662, reverse strand). Ensembl gene ENSG00000206772.
Homologues: Orthologues: mouse Gm26138 (97% identical), pig U6 (90% identical). Paralogues in human: RNU6-41P (98% identical), RNU6-12P (96% identical), RNU6-13P (96% identical), RNU6-25P (96% identical), RNU6-32P (96% identical), RNU6-1 (95% identical), RNU6-15P (95% identical), RNU6-17P (95% identical), RNU6-18P (95% identical), RNU6-2 (95% identical), RNU6-3P (95% identical), RNU6-4P (95% identical), and 1287 more.